CD276 (CD276 molecule)
Diseases named in the same sentence as CD276 in open-access papers (continued):
Sharing a sentence is not in itself a finding about the gene and the disease.
colorectal cancer (101 papers, 2013 to 2026). A primary or metastatic malignant neoplasm that affects the colon or rectum. "Analysis of tissue sections obtained from colorectal cancer patients indicated a positive correlation between CD276 expression on tumor cells and CD68+ tumor associated macrophages (TAM) infiltration." (PMID 34290311, 2021). "Nuclear localization of CD276 in colorectal cancer, high CD276 expression in pancreatic cancer and on tumor-associated endothelial cell in ovarian carcinoma were reported to be a predictive parameter for reduced survival rate." (PMID 34290311, 2021). "CD276 overexpression, on the other hand, was linked to anti-apoptosis in colorectal cancer through activation of Jak2-STAT3 signaling pathway, and as a result, increased expression of anti-apoptotic protein Bcl-2." (PMID 32188505, 2020). "In colorectal cancer, nuclear CD276 expression strongly predicts poor outcome and associates with clinicopathological parameters." (PMID 27329595, 2016). "B7H3 (also known as CD276) regulates ferroptosis sensitivity in colorectal cancer (CRC) cells by downregulating SREBP2 expression." (PMID 40853521, 2025). "It has further been shown that CD276 (B7-H3) increases the ability of colorectal cancer cell lines to resist apoptosis by activating the Janus kinase 2-signal transducer and activator of transcription 3 (JAK2-STAT3) pathway." (PMID 39911580, 2024). "Jiang and colleagues have shown that upregulated CD276 in primary colon adenocarcinoma can enhance the expression of CD133 and CD44 associated with the EMT in colorectal cancer." (PMID 38398141, 2024). "Consistently, the introduction of CD276 into mice with colorectal cancer was shown to inhibit tumor growth and reduce secondary metastasis." (PMID 38637557, 2024). "In patients with colorectal cancer, CD276 was expressed in the cell membrane/cytoplasm in 86% of the patients, followed by the stroma, whereas the expression level was low in the nucleus." (PMID 36717836, 2023). "CD276 (B7-H3), a member of the B7 superfamily, was shown to be overexpressed in colorectal cancer, pancreatic cancer, diffuse brain glioma, non-small cell lung cancer and head and neck cancers, and enhanced cancer progression." (PMID 33995379, 2021). "CD276 may further stimulate the nuclear factor-κB (NF-κB) pathway and enhance angiogenesis in colorectal cancer." (PMID 39911580, 2024). "CD276 (B7-H3), a member of the B7 family of immune checkpoint proteins, have been found to be low expressed in normal tissues and high expressed in a variety of malignancies, including colorectal cancer." (PMID 38260829, 2023). "CD276 impacts colorectal cancer cell migration through the Jak2/Stat3/MMP-9 signaling pathway." (PMID 35296518, 2022). "In this regard, inhibition of CD276 was found to reduce tumor growth, prolong survival and improve CD8+ T cell and NK cell infiltration in mouse models of colorectal cancer and osteosarcoma." (PMID 36268020, 2022). "Additionally, B7H3/CD276, an immune checkpoint molecule, has been identified as a potential regulator of ferroptosis resistance in colorectal cancer cells." (PMID 39624080, 2024). "B7H3 (CD276), an immune checkpoint protein, plays a role in tumor progression and resistance to therapy, and correlates with poor prognosis in various cancers, including colorectal cancer." (PMID 39335702, 2024). "A previously published study also revealed that CD276 may regulate glucose metabolism and chemotherapy resistance by controlling the expression of hexokinase 2 (HK2) in colorectal cancer cells." (PMID 36717836, 2023).
glioblastoma (100 papers, 2016 to 2026). The most malignant astrocytic tumor (WHO grade IV). "Its expression is typically low in normal tissues but elevated in various cancers, and CD276 overexpression has been linked to adverse patient outcomes in several cancer types, including glioblastoma." (PMID 40136662, 2025). "Qi and colleagues demonstrated that an eight-gene risk signature based on fatty acid catabolic metabolism in glioblastoma had high prognostic value and that this signature significantly correlated with gene expression of the immune checkpoint markers B7-H3 (CD276) and HAVCR2 (TIM-3)." (PMID 40072074, 2025). "Consistent with our IHC findings, elevated levels of CD276 expression were found in glioblastoma, which might be associated with its role in facilitating immune evasion." (PMID 38365809, 2024). "The close association between CD276 and microvascular proliferation in (glioblastoma multiforme) GBM biopsies was clearly demonstrated, permitting qualitative as well as quantitative tissue analyses." (PMID 33557152, 2021). "As such, previous research has found increased expression of CD276 mRNA and protein in glioblastoma as compared to healthy brain tissue." (PMID 40469103, 2025). "To confirm these findings, we screened several patient-derived stem cell-enriched glioblastoma cells (pGSCs) for their CD276 surface expression by flow cytometry." (PMID 40469103, 2025). "Using this powerful new technology, we have specifically studied the tissue distribution of Iba1+ and CD163-expressing macrophages in human glioblastoma biopsies in relation to CD276+ GSCs, with the aim of gaining insights into their in situ relationship." (PMID 40136662, 2025). "In glioblastoma, CD276 expression correlated with CSC-related genes and MYC, and CD276 was suggested as an inhibitor of the TGF-β pathway and differentiation of CSCs." (PMID 40175626, 2025). "One aspect of this work focuses on the evaluation of the relationship between the presence of CD276 immunoreactive cells and patient survival in glioblastoma as an example of system outcome predicted from WSI graph data." (PMID 38398141, 2024). "Based on these findings, we established a risk signature comprised of CD276, TNFRSF14, TNFSF14, TNFSF4, CD40, and TNFRSF18 to predict OS and response to immune checkpoint blockade in glioblastoma patients." (PMID 38365809, 2024). "We have used two datasets for our study, our own CD276 dataset and glioblastoma (GBM) dataset from TCGA." (PMID 38398141, 2024). "Similar associations were observed in the CGGA-glioblastoma cohort for CD40, CD276, TNFRSF14, and TNFSF14, except for TNFSF4 and TNFRSF18." (PMID 38365809, 2024). "B7-H3, also known as CD276, is highly aberrantly expressed in a variety of tumor tissues, such as glioblastoma 9 and gastric cancer 10 tissues, but is rarely expressed in normal tissues." (PMID 37705739, 2023). "For instance, all 18 CD276+ glioblastomas were highly resistant to the ADC, with IC50 values greater than 1 nM, while all 6 CD276+ neuroblastomas were highly sensitive, with IC50 values generally much less than 1 nM." (PMID 38019654, 2023). "We have taken advantage of the capability of PathoFusion to identify pathological changes characteristic of glioblastoma and to correlate the location of CD276 immunoreactive cells." (PMID 35884502, 2022). "We illustrate our approach using the detection of CD276 immunoreactive cells in glioblastoma as an example." (PMID 35884502, 2022). "We have used glioblastoma biopsies and CD276 as an immunochemical marker for testing the extended PathoFusion system." (PMID 35884502, 2022). "The anti-tumor function of CAR-T cells genetically engineered to target CD276 in glioblastoma was demonstrated in vivo, and in vitro." (PMID 36555243, 2022). "According to recently published literature, it seems possible that “halo cells” represent a type of CD276-expressing cancer stem cells, i.e., glioblastoma stem cells (GSCs)." (PMID 35884502, 2022).
glioblastoma (continued). "On the basis of detailed microscopic analyses of CD276-labelled glioblastoma biopsies, we have identified a subpopulation of cells which, because of their strong perinuclear immunoreactivity, we have tentatively termed “halo cells”." (PMID 35884502, 2022). "Adjacent tissue sections obtained from glioblastoma cases were processed for hematoxylin and eosin (H&E) and immunohistochemical (CD276) staining." (PMID 33557152, 2021). "Interestingly, the number of CD276 GSCs in the material available to us varied significantly in line with the histological heterogeneity of glioblastoma and the inherent variability of the neurosurgical bioptic process." (PMID 38398141, 2024). "Meanwhile, an MMP-2 activated nanoparticle carrying EGCG dimer and immune checkpoint B7-H3 (CD276) bispecific antibodies was reported to induce the elimination of glioblastoma through increasing the ferroptosis and strengthening the immune checkpoint blockade treatment." (PMID 38348027, 2024). "We used CD276, a protein of interest in glioblastoma, as a marker and focused our analysis on a subpopulation of labelled cells which may represent glioblastoma stem cells (GCS)." (PMID 35884502, 2022). "The results revealed that glioblastomas of ArMRS high-risk group had significantly higher expression levels of CD44, CD48, CD276 (B7-H3), and PD1 (PDCD1) compared to low-risk group in the TCGA cohort, suggesting higher ArMRS may indicate more abundant expression of immunotherapy targets." (PMID 37214463, 2023). "Accordingly, irradiation-induced upregulation of CD276 in glioblastoma cells did not lead to enhanced killing by the CD276-specific CAR-NK cells." (PMID 40469103, 2025). "While intrinsically NK-sensitive K562 cells were lysed to a very similar extent as the glioblastoma cells, no increase in lysis rates over parental NK-92 cells was found for Jurkat j16 cells, demonstrating CD276 specificity of CAR NK-92 cells lysis." (PMID 40469103, 2025). "While incubation with parental NK-92 did not lead to lysis of the pGSCs, CD276-directed CAR NK-92 cells lysed all glioblastoma cell lines." (PMID 40469103, 2025). "Notably, genes such as CD276 (B7-H3), GATA3, and LGALS3 (galectin-3) have been shown to play significant roles in glioblastoma prognosis." (PMID 39068393, 2024). "In addition, according to the Ivy Glioblastoma Atlas Project database, the distribution of MAP2K3 was consistent with the distribution of macrophage markers CD68 and CD276." (PMID 38938778, 2024). "In addition, we obtained representative IHC staining images of CD276, TNFSF4, TNFRSF14, CD40, TNFSF14, and TNFRSF18 in both normal tissues and glioblastoma samples from the Human Proteome Atlas." (PMID 38365809, 2024). "Notably, the most relevant one, CD276 (B7H3), is a potential target of CAR-T products, which exhibit promising efficacy in the treatment of glioblastoma both in vitro and in vivo." (PMID 37006287, 2023). "For example, RGCC, SPP1 (osteopontin), GPNMB, and APOE are highly expressed in hepatocellular carcinoma (HCC), whereas PLVAP (PV1), CD276 (B7-H3), and ESM1 are predominantly expressed in glioblastoma (GBM)." (PMID 41303611, 2025). "B7-H3 (CD276) is an immune checkpoint molecule overexpressed in many cancer types, including 76% of glioblastoma (GBM) tumors, the most common primary malignant brain tumor in adults." (PMID 40957993, 2025). "Additionally, previous studies have stated that CD276 (B7-H3), GATA3, and galectin-3 enable prognosis prediction in glioblastoma, and that correlation between lower balance of Th2 helper T-cells and lower expression of PD-L1/PD-1 axis genes also estimate prognosis in glioblastoma." (PMID 39707577, 2024). "On the other hand, the expression of B7 homolog 3 protein (B7-H3, CD276) was identified as an immune checkpoint molecule for glioblastoma (GBM), but not for EPN-ZFTA." (PMID 37322295, 2023).
glioblastoma (continued). "Interestingly, cytokine secretion by CD276-targeted CAR NK-92 cells was more pronounced after co-incubation with non-malignant cell lines and K562 cells, whereas all glioblastoma cells only led to moderate TNFα and IFNγ secretion." (PMID 40469103, 2025).
neuroblastoma (94 papers, 2009 to 2026). Neuroblastoma (NB) is the most common solid, extracranial childhood tumor. "CD276 is associated with diseases such as immunodeficiency and neuroblastoma." (PMID 39771050, 2024). "B7-H3 (CD276) is overexpressed in many pediatric solid tumors including pediatric sarcoma and neuroblastoma, with limited expression in normal tissue." (PMID 40469285, 2025). "Previous researches have shown that CD276, an important IC molecule, is often highly expressed in neuroblastoma and non-small cell lung cancer cells, inhibits the cytotoxicity of NK cells." (PMID 35514986, 2022). "B7-H3 has been characterized as a pan-cancer antigen overexpressed in a variety of solid tumors including neuroblastoma and pediatric sarcomas, for which CD276-CAR-T cells are being investigated." (PMID 35456250, 2022). "Since combined expression of GPC2 and CD276 is observed in 95% of neuroblastoma samples, these BiCisCAR T cells have specificity for a greater proportion of cancer cells compared to single target CAR T cells." (PMID 35968786, 2022). "One study reports that neuroblastoma cells express CD276 on the surface, which protects them from NK cell-mediated lysis." (PMID 34680929, 2021). "We previously showed that CD276-CAR NK-92 cells were effective in targeting neuroblastoma cells in vitro." (PMID 33925968, 2021). "B7-H3 (CD276) is a checkpoint molecule expressed at high levels on many pediatric solid tumors including neuroblastoma." (PMID 30459759, 2018). "Since tumor escape due to immunoediting is a key challenge to implementing CAR T cells in solid tumors, Tian and colleagues examined the ability of BiCisCAR T cells to overcome heterogenous antigen expression by using neuroblastoma cell lines that had CRISPR mediated ablation of GPC2 or CD276." (PMID 35968786, 2022). "Aiming at controlling neurotoxicity of GD2-CAR-T cells, SynNotch gated CAR-T cells recognizing GD2 ganglioside as the gate and B7H3, i.e., CD276, as the target, were assayed against neuroblastoma in vitro and in xenograft mice demonstrating the specificity and efficacy of the therapy." (PMID 34204326, 2021). "Similarly, we observed the upregulation of CD276 (B7-H3) in MYCN-A neuroblastoma." (PMID 39860532, 2025). "Here, we aimed to identify optimal CARs against glypican 2 (GPC2) or CD276 (B7-H3), which were highly but heterogeneously expressed in neuroblastoma (NB), a lethal extracranial solid tumor of childhood." (PMID 35852863, 2022). "B7-H3 (CD276), located on chromosome 15, is an immune checkpoint protein over-expressed on multiple malignancies including neuroblastoma." (PMID 39489087, 2024). "Protein abundance of KCNH1 was comparable to targets under development in neuroblastoma including NCAM1, L1CAM and CD276, and higher than other known immunotherapeutic targets such as ALK and GPC2." (PMID 38895237, 2024). "While GPC2 CARs lose cytotoxicity in the context of GPC2 ablation and CD276 lose cytotoxicity in the context of CD276 ablation, BiCisCARs retained cytotoxicity with both GPC2KO and CD276KO neuroblastoma cells." (PMID 35968786, 2022). "Compared with single target CAR T cells, BiCisCAR T cells not only had comparable in vitro cytotoxicity against neuroblastoma cells coexpressing GPC2 and CD276, but they also secreted greater amounts of cytokines, such as IFN-γ and TNF-α." (PMID 35968786, 2022). "B7H3 (CD276), a checkpoint molecule expressed in neuroblastomas, is another candidate for CAR therapies of neuroblastoma." (PMID 33322408, 2020). "More recently, B7-H3 (CD276) has become a validated pediatric cancer target for immunotherapy in pontine gliomas and neuroblastomas." (PMID 33330054, 2020). "In the analysis of MYCN-Amplified Neuroblastoma (NBL-MYCNA) our algorithm identified one of the most interesting current targets, CD276 (B7-H3)." (PMID 23251904, 2012).
neuroblastoma (continued). "SCAN-ACT identified 174 monospecific CAR-T targets in GBM, including several established GBM CAR-T targets such as CD276, EGFR, IL13RA2, ROBO1, as well as targets studied in different diseases like GPC2 in neuroblastoma, IL11RA in osteosarcoma, or DLL3 in lung cancer." (PMID 40814001, 2025). "In the present study, we evaluated whether the recently established NK cell line CD276-CAR NK-92, that proved to be effective in targeting neuroblastoma, could also be an effective cellular product for the treatment of melanoma." (PMID 33925968, 2021). "There have been no previous studies on CD276-CAR-NK-92 cells for the treatment of AML, but their efficacy has been tested against other malignancies such as neuroblastoma or melanoma." (PMID 36361619, 2022). "Moreover, CD276-CAR T cells showed efficacy in preclinical models of pancreatic ductal adenocarcinoma, ovarian cancer, and neuroblastoma without toxicity." (PMID 37924157, 2023).